E2F6 (E2F transcription factor 6)
Diseases named in the same sentence as E2F6 in open-access papers (continued):
Sharing a sentence is not in itself a finding about the gene and the disease.
myocardial ischemia (1 paper, 2021). A disorder of cardiac function caused by insufficient blood flow to the muscle tissue of the heart. "Motif enrichment analysis showed that Gm18840 bound to the region enriched for the EWSR1-FLI1, E2F6, and ZNF263 motifs, indicating that Gm18840 might regulate the transcriptional activity of these transcription factors and contribute to myocardial ischemia–reperfusion injury." (PMID 34322480, 2021).
nasopharyngeal carcinoma (1 paper, 2018). A carcinoma arising from the nasopharyngeal epithelium. "What is more, E2F6 functions as a tumour suppressor in nasopharyngeal carcinoma." (PMID 30487158, 2018). "Restoring E2F6 expression in nasopharyngeal carcinoma impairs proliferation." (PMID 30487158, 2018).
non-small cell lung carcinoma (1 paper, 2021). A group of at least three distinct histological types of lung cancer, including non-small cell squamous cell carcinoma, adenocarcinoma, and large cell carcinoma. "We further confirmed decreased E2F6, L3MBTL2, and PCGF6 protein levels in MGA mutant human non-small cell lung cancer lines H2291 and Lou-NH-91 when compared to wild-type lines such as NCI-H1975, NCI-H23, and 91T." (PMID 34236315, 2021).
pancreatic adenocarcinoma (1 paper, 2020). "In addition, ONCOMINE analysis revealed no significant contrast in the transcriptional levels of E2F2, E2F4, and E2F6 between pancreatic adenocarcinoma and normal samples." (PMID 33604289, 2020).
prostate tumor (1 paper, 2019). "Mocetinostat, a clinical phase II HDACi, has been described as involving miR-31 in the inhibition of E2F6 (E2F transcription factor 6), leading to apoptosis of the prostate tumor cells." (PMID 31658720, 2019).
retinoblastoma (1 paper, 2010). A malignant tumor that originates in the nuclear layer of the retina. "Eight E2F family members have been identified so far, E2F1 to E2F8, whereas E2F1 to E2F6 share the same structure: conserved DNA binding and dimerization domains, and, except for E2F6, have domains for transactivation and binding Pocket Proteins (PP): p107, p130 and Rb (Retinoblastoma)." (PMID 21637599, 2010).
sarcoma (1 paper, 2025). A usually aggressive malignant neoplasm of the soft tissue or bone. "Several of the identified MLS- and EWS-specific transcription factors are implicated in FET sarcoma oncogenesis; for example, increased gene expression of the EWS-specific transcription factors HOXD11, SOX6, MEIS1, and E2F6 were reported to be involved in EWS malignancy." (PMID 40988026, 2025).
squamous cell carcinoma (1 paper, 2013). A carcinoma arising from squamous epithelial cells. "We found that E2F6, HMGA1, IRF1, and TFDP1 were upregulated and RBL1, SUV39H1, and HNRPD were downregulated or aberrantly expressed in adenocarcinoma and squamous cell carcinoma, which are the sub-types of NSCLC." (PMID 24564251, 2013). "Frozen NSCLC tissue-based microarray analysis revealed that E2F6, TFDP1, SUV39H1, and HMGA1 are significantly upregulated in both the adenocarcinoma and squamous cell carcinoma samples." (PMID 24564251, 2013). "Therefore, combining the microarray and qPCR results, upregulation of E2F6, HMGA1, IRF1, and TFDP1 and downregulation or no expression of SUV39H1, RBL1, HNRPD can be used as diagnostic markers of NSCLC, and, in particular, adenocarcinoma and squamous cell carcinoma." (PMID 24564251, 2013).
teratocarcinoma (1 paper, 2013). A germ cell tumor characterized by the presence of an embryonal carcinoma component and a teratoma component. "They reported that human stem cells and teratocarcinoma cells show a selective reduction in the expression of E2F1, E2F2, E2F3 and p105 (encoded by NFKB1) and enhanced expression of E2F4, E2F5, E2F6 and p130 (encoded by RBL2) compared with human normal somatic IMR90 cells." (PMID 24355041, 2013).
viral infection (1 paper, 2016). "In the context of viral infection, abnormal expression of E2F6 was observed as an independent contributor to nasopharyngeal carcinogenesis." (PMID 27548379, 2016). "In the context of viral infection, abnormal expression of E2F6 was found as an important contributor to nasopharyngeal carcinogenesis." (PMID 27548379, 2016). "The results showed that E2F6 could be up-regulated at 1 day post-infection (dpi) in both wild-type and mutant virus infection." (PMID 27548379, 2016).
Wilms tumor (1 paper, 2024). An embryonal neoplasm characterized by the presence of epithelial, mesenchymal, and blastema components. "Okutsu reported the aberrant expression of IGF2-AS in Wilms’ tumor and suggested the potential of IGF2-AS as one of the candidate Wilms’ tumor genes, while research about SLC9A3-AS1 reported the carcinogenic effect on NPC cells exerted by SLC9A3-AS1 through adjusting the miR-486-5p/E2F6 axis." (PMID 38635069, 2024).
tumor (42 papers, 2013 to 2026). "Using primers common to all E2F6 transcript variants, high levels of cDNA were found in the tumor samples relative to the normal tissue." (PMID 31768102, 2019). "Functional analyses of miR-28-5p revealed tumor suppressive properties caused by the inhibition of Rap1b, E2F6, IGF-1, IL-34, and AKT." (PMID 31921670, 2019). "The E2F6 expression level was significantly associated with tumor grade (P < 0.0001)." (PMID 31508283, 2019). "M2 TAMs-derived exosomes contain LINC01592, which can be transported into tumor cells and subsequently facilitate tumor growth by inhibiting the E2F6/NBR1/MHC-I signaling pathway." (PMID 40607254, 2025). "Restoring E2F6 levels restored the tumorigenic effects of miR-185, indicating that the miR-185/E2F6 axis is crucial for tumor regulation in ES." (PMID 40429954, 2025). "Analysis of TCGA-LIHC database showed that E2F4, E2F5, and E2F6 were upregulated in tumor tissues of HCC compared to normal tissues." (PMID 38166853, 2024). "The tumor-promoting effects of LINC01592 were significantly reduced through the disruption of E2F6/NBR1/MHC-I signal axis." (PMID 37915049, 2023). "The siRNA or antibody blockade of LINC01592/E2F6/NBR1/MHC-I greatly diminished LINC01592's tumor-supporting effects and suppressed M2-dependent tumor growth." (PMID 37915049, 2023). "In this investigation, it was demonstrated that the origin of LINC01592 from M2-TAM exosomes enhanced evasion of the immune system by the tumor through the activation of E2F6/NBR1/MHC-I signaling pathway." (PMID 37915049, 2023). "Several studies have clarified the effect of the ubiquitin-proteasome pathway on the function of E2F1 and consequent tumour development 40, 50, 51, while posttranslational modification of E2F6 in HCC cells is poorly understood." (PMID 35844791, 2022). "Gene group 2 displayed a significant upregulation of E2F transcription activators (E2F1, E2F2, E2F3, and E2F6) and tumor-specific transcription factors (MYCN, RUNX1, and GABPB1) in advanced Rb." (PMID 35626705, 2022). "The results demonstrated that downregulation of E2F6 inhibited tumour growth and extended the survival time." (PMID 34381702, 2021). "We determined MAX, MGA, MYC, L3MBTL2, E2F6, and RNA polymerase II (RNA pol2, all phosphorylated forms) occupancy in Mga-inactivated and control (empty) KP tumor-derived cells lines." (PMID 34236315, 2021). "The E2F6 expression in LGG showed a significant positive correlation with tumor purity and infiltrating levels of B cells, CD8+ T cells, macrophages, neutrophils, and dendritic cells but not with CD4+ T cells." (PMID 33381564, 2020). "This work revealed that LINC00607 worked as an miR-607 sponge to upregulate E2F6 expression, which promoted tumor proliferation in OS." (PMID 33585204, 2020). "Further, we identified that LINC00607 acted as an miR-607 sponge to modulate E2F6 expression and directly regulated the in vivo tumor growth of OS." (PMID 33585204, 2020). "Next, we examined the E2F6 expression in tumor tissues by RT-PCR to understand the role of E2F6 in OS and found that its expression was relatively higher than the adjacent normal tissue sample." (PMID 33585204, 2020). "As a result, GHET1, IGF2BP2 and E2F6 presented elevated expression in CC tissues compared with non-tumor tissues." (PMID 31682716, 2020). "Among selected hypoxia-related transcripts, we observed two significantly upregulated transcripts (Lox and Adm), and three significantly downregulated transcripts (Cdk20, E2f6, and Ccnd1) in tumor-bearing versus vehicle mice." (PMID 32151276, 2020). "In MCF-10A cells, for which expression was already low compared to the tumor cell lines, E2F6 became almost undetectable after transfection with each of the specific si-E2F6s." (PMID 31768102, 2019). "In the tumor cell lines, the impact of transfection varied among the three si-E2F6s, but in all cases there was a reduction in detectable E2F6 compared to scrambled si-RNA." (PMID 31768102, 2019).
tumor (continued). "Combined with the CC enrichment analysis results, E2f6-related histone modification may also promote the progression of HNSCC by inhibiting the expression of tumor suppressor genes." (PMID 36855110, 2023). "Moreover, E2F6 was proven to repress a set of tumor suppressors including BRCA1 genes via covalent histone modification." (PMID 36855110, 2023). "Thus, our findings provide the LINC00607/miR-607/E2F6 axis as a novel lncRNA-related pathway to control tumor proliferation in OS, which provides novel potential therapeutic targets for OS." (PMID 33585204, 2020). "Subsequently, we investigated whether pharmacological inhibition (JSH‐23) of NF‐κB, a critical regulator of E2F6, inhibits tumor growth and sensitizes TMZ in orthotopic patient‐derived GBM xenograft mouse model." (PMID 31508283, 2019). "Our findings in this study have identified new parameters (miR-31, E2F6, Bad) that may be used to monitor tumor response to mocetinostat." (PMID 27551526, 2016). "Comparing the E2F6 cDNA levels at different tumor stages revealed each stage to have significantly more cDNA than normal tissue, especially when using E2F6 common primers (P < 0.001; Mann–Whitney U test), with a trend to suggest that expression may increase further as the tumor progresses." (PMID 31768102, 2019). "We further studied whether miR-424 functioned as a tumor suppressor gene by targeting E2F6." (PMID 29371986, 2017). "Another analogous study suggests that LINC01592 secreted by M2-TAMs binds to E2F6 in tumor cells, enhancing NBR1 transcription, leading to MHC-I degradation and defective anti-tumor immunity." (PMID 39223632, 2024). "Generally, the E2F6 regulates the gene expression of proteins involved in cell proliferation and the CDK10 acts as a tumor suppressor." (PMID 37396909, 2023). "TF factor motif analysis within H3K27ac peaks revealed 29 MG63-specific TF binding sites, including those for EOMES, PRDM1, EPAS1 (HIF2A), E2F6, and MYC/MAX, which reflect known early development, tumor-initiation, and stemness factors (Worksheet 1)." (PMID 37228489, 2023). "The tumor-promoting impacts of LINC01592, as well as the growth of M2-type macrophage-driven tumors, were significantly suppressed by the interruption of E2F6/NBR1/MHC-I signaling through the effect of siRNA or the corresponding antibody blockade." (PMID 37915049, 2023). "MGA, MAX, E2F6, and L3MBTL2 were seen to bind several thousand promoters in MGA-expressing KP tumor cells suggesting that the PRC1.6 complex plays a broad role in tumor cell gene expression." (PMID 34236315, 2021). "This study has several limitations: although we have recently verified the role of the E2F6 ceRNA network in the epigenetic control of miR-193a, the role of such a network in the regulation of PBX1 and the subsequent anti-tumor immune response requires experimental validation." (PMID 35216394, 2022). "We then investigated the relationships between the eight E2Fs and tumor immunology and found that E2F1, E2F3, E2F5, E2F6, and E2F7 expression was positively correlated with many immune cells, which might explain their favorable prognostic value." (PMID 34617871, 2021). "In this report, we demonstrated that the expression of E2F6 in LC tissues was higher than that in normal tissues, but this expression was not correlated with tumor stage in patients with LC." (PMID 29754146, 2018). "We find that in normal samples and superficial tumor samples, the activity for the modules of the E2F1, E2F2 and E2F3 target genes is lower than in invasive tumors, as opposed to the target genes of the inhibitory transcription factors E2F4 and E2F6." (PMID 26925094, 2016). "However, the function of E2F6 in CC tumor progression and its relation with GHET1 have never been explored." (PMID 31682716, 2020).
tumor (continued). "The results showed that the expression levels of E2F2, E2F3, E2F6, and E2F8 are significantly correlated with the tumor stage of PAAD patients, while the expression levels of E2F1, E2F4, E2F5 and E2F7 are not correlated with the tumor stage of PAAD patients." (PMID 33604289, 2020).
cancer (37 papers, 2009 to 2025). A tumor composed of atypical neoplastic, often pleomorphic cells that invade other tissues. "Our findings also infer that E2F6 or other E2F transcription factors can be targeted as potential therapeutic intervention strategies in EBV-associated cancers." (PMID 27548379, 2016). "This analysis revealed that activities of TCF3 and E2F6 are associated with cell cycle process indicating a potential function in cancer development." (PMID 27818995, 2016). "In the “OncoPrint” and “Cancer Types Summary” schematics, the gene alteration of E2F6 was 7% in the selected HNSCC samples." (PMID 36855110, 2023). "The TCGA database analysis also revealed that expression of NBR1 and E2F6 is elevated in cancer tissues, and their expression was inversely related to patient outcome." (PMID 37915049, 2023). "A higher level of LINC01592/E2F6/NBR1 expression was detected in cancer tissues, especially in III + IV." (PMID 37915049, 2023). "Some TFs with cancer-related biological functions also showed high Jaccard scores with G4-II, such as E2F6, IRF1, and MYC." (PMID 36092921, 2022). "Regarding E2F6, the expression was observed to be down-regulated in PCa compared to benign tissues (benign vs. cancer = 1.85 ± 0.03 vs. 1.78 ± 0.01, p < 0.05)." (PMID 35531101, 2022). "It has also been reported that downregulation of lncRNA CASC2 mediated by E2F6 predicts worse outcomes and facilitates cancer progression in GC patients." (PMID 34532281, 2021). "Previous studies have revealed that E2F6 exerts an oncogenic role in the progression of cancers and functions as a target gene of some miRNAs." (PMID 32536825, 2020). "Concerning cancer cell lines, E2F6 was also found to be highly expressed in MCF-7 and T-47D cells (both are ER-positive) as well as MDA-MB-231 cells (ER-negative)." (PMID 31768102, 2019). "KIF2C and KIF20A were reported, in a study based on ChIP-chip assays, as the target of E2F family including E2F1, E2F4, and E2F6 in normal and cancer cells of breast tissue." (PMID 30813560, 2019). "Remarkably, USP22 knockout had pronounced effects on expression of these important cancer-associated gene sets such as c-Myc, E2F, and selected genes including ALDH1A3, CCNE1/G1, E2F6, HOXA1, MMP9, NFKB2, TP63, TPM4, SET7/9 were validated by qRT–PCR." (PMID 31842906, 2019). "We predicted that further replication stress in cancer cells would increase the proportion of cells with sub-G1 DNA content when E2F6 expression was reduced." (PMID 31768102, 2019). "Among the enriched targets that are more strongly associated with cancer (i.e., RAP1B, N4BP1, MAPK1, and E2F6), almost all are protumoral." (PMID 29085832, 2017). "While siRNA knockdown of E2F6 sensitized cancer cells to mocetinostat-induced apoptosis, overexpression of E2F6 blocked mocetinostat-induced apoptosis." (PMID 27551526, 2016). "We notice similar result like gene-level data, coexpressed target transcript of Sam68 are involved in cancer-specific processes such as cell cycle, protein N-terminal acetylation, cell cycle phase transition, E2F6 transcription regulation in KIRP and LUAD39–41." (PMID 31366900, 2019). "In cancer cells, E2F6 overexpression might be favored as a bypass mechanism during replicative stress, facilitating increased proliferation." (PMID 31768102, 2019). "Si-E2F6#2 was the best in decreasing E2F6 in all the studied cancer cells." (PMID 31768102, 2019). "However, in cancer cells, E2F6 has been shown to play a dual role as a transcriptional activator and repressor." (PMID 31768102, 2019). "In conclusion, these findings raise the possibility that E2F6 could be developed as a therapeutic target in cancers, where its expression is essential." (PMID 31768102, 2019). "By targeting DNMT1, RhoA/Cdc42, and E2F6, miR-185 has been shown to induce cell cycle arrest and apoptosis, in addition to inhibiting proliferation and invasion in cancer cell lines and xenograft mouse models of various cancers." (PMID 26930719, 2016).
cancer (continued). "Based on these studies, it is also important to suggest the EBNA3C may affect the functions of these cellular antigens and related pathways through E2F6, which may provide new insights for targeting E2F transcription factors in EBV-associated cancers as potential therapeutic intervention strategies." (PMID 27548379, 2016). "Therefore, in the context of EBV infection, EBNA3C-mediated E2F6/E2F1 regulation may offer novel insights to further understand the important role of EBV latent antigens in E2Fs-related cellular functions or cancer development." (PMID 27548379, 2016). "The investigation conducted has revealed a significant molecular interaction between TAMs and EC via the LINC01592/E2F6/NBR1/MHC-I axis, which facilitates the progression of malignant tumors." (PMID 37915049, 2023). "A specific gene with highly differential expression, such as RNF8 in THYM, YPEL2 in LAML, and E2F6 in DLBC, indicates a strong correlation between this gene and the corresponding cancer." (PMID 31709182, 2019). "The results showed that these hub genes exhibited distinct expression patterns in different cancers, such as RNF8 in THYM, YPEL2 in LAML and E2F6 in DLBC, which indicated the potential relation of these genes with the corresponding cancer." (PMID 31709182, 2019). "Our analysis showed that AATF, LGALS3, and SRC are up regulated in 8/13 of cancer models, and CDC2L2, E2F6, LGALS9, PDCD8, RELB, TRADD, and TRAF2 in 7/13." (PMID 19402918, 2009). "However, the effects of E2F2, E2F4, E2F6, and E2F8 on prostate etiology and cancer growth are poorly understood." (PMID 37569304, 2023). "The notably high overlapping ratios were discerned for TFs playing critical roles in transcription pre-initiation or RNA polymerase activities, e.g., UBTF, TAF1, and POLR2A, in addition to others, like E2F6, IRF1, and MYC, which are involved in cancer-related processes." (PMID 36092921, 2022). "However, little is known about the effects of E2F2, E2F4, E2F6, and E2F8 on prostate pathogenesis and cancer progression." (PMID 35531101, 2022). "In contrast, MCF-10A cells, which are not cancer cells, remained viable even though the E2F6 protein levels were reduced the most." (PMID 31768102, 2019). "A pan-cancer survival rate analysis was also performed to assess the prognostic values of these genes, and the results showed that these overlapping genes might be signatures in various cancers, such as RNF8 in KIRC, RB1 in OV and E2F6 in LIHC." (PMID 31709182, 2019). "TFPD1, E2F6, IRF1, and HMGA1 are upregulated in all cancer samples." (PMID 24564251, 2013). "In addition, the E2F6 expression of GBM was positively related to cancer purity, CD8+ T cells, and macrophages but not with neutrophils." (PMID 33381564, 2020).